ENO1 (enolase 1)
Diseases named in the same sentence as ENO1 in open-access papers (continued):
Sharing a sentence is not in itself a finding about the gene and the disease.
cancer (continued). "Alpha-enolase (ENO1), a famous glycolytic enzyme functioning during aerobic glycolysis, was found in nearly all parts of adult human, and contributed to the Warburg effect in cancer cells." (PMID 34772911, 2021). "Indeed, overexpression of PlgRs, including actin, enolase-1, cytokeratin 8, and annexin II-S100A10, has been associated with poor prognosis and resistance to chemotherapy in patients with cancer." (PMID 34082810, 2021). "In addition to glycolytic activity, ENO1 appears to have various cellular functions and subcellular localizations, performing important role in other pathophysiological processes in cancer." (PMID 33628097, 2021). "These compounds such as ZINC1304634 7, ZINC16124623 8, ZINC1702762 9, tropolone 10, pyridine 11 and hydroxyquinoline 12 may be considered promising anticancer agents for further development, and could fight the metabolism of cancer by inhibiting ENO1 99,100." (PMID 34671213, 2021). "The levels of FAP and ENO1 in cancer tissues could predict the overall survival and recurrence-free survival in patients." (PMID 34035230, 2021). "ENO1 is required for maintaining the Warburg effect of cancer cells." (PMID 34671213, 2021). "The mTOR/HIF1α/ENO1 pathway can also enhance glycolysis in other cancers." (PMID 33968941, 2021). "In summary, MSPA exhibits anti-cancer effects by simultaneously targeting ENO1, ALDOA, and FH." (PMID 34681284, 2021). "p15INK4B also binds and inhibits enolase-1, a glycolytic enzyme upregulated in most cancer types." (PMID 33824349, 2021). "The therapeutic inhibitor targeting to the ENO1 might offer the promising new treatment options for cancer treatment." (PMID 34671213, 2021). "Some function model studies have shown that ENO1 is a potential target for cancer treatment." (PMID 34671213, 2021). "PPIs with participation of ENO1 could be regarded as an important element in the initiation of cancer-related events." (PMID 34440098, 2021). "The switching of ENO1 location is related to the pathology of cancer and inflammatory." (PMID 34671213, 2021). "As one of the highest ranked down-regulated hub-bottlenecks of our network, ENO1 could be important in explaining the benefits of exercise training in diseases such as cancer, as its up-regulation is part of the cancer growth pathway." (PMID 34659659, 2021). "A landmark study suggests that citrullinated ENO1 peptides could be an effective vaccines for cancer immunotherapy." (PMID 34671213, 2021). "ENO1 play an important role in the process of cancer development." (PMID 34671213, 2021). "And the development of novels anticancer agents that targets ENO1 may provide a more attractive option for the treatment of cancers." (PMID 34671213, 2021). "In addition, some studies have reported that the prognostic effect of ENO1 in various cancers was opposite." (PMID 34504528, 2021). "The pharmacological inhibition of ENO1 with phosphonoacetohydroxamate (PhAH) was selective to inhibit enzymatic activity in cancer cells, where PhAH also significantly reduced proliferation; instead, in normal human fibroblasts or normal pancreatic cells, PhAH was not effective." (PMID 33804240, 2021). "In the cytoplasm, ENO1 provides a rapidly available supply of ATP to cells and, interacting with the cytoskeletal system, supports the rapid growth, proliferation, and movement of cancer cells." (PMID 33628097, 2021). "Together, our findings suggest that Ndufa4l2 may play a fundamental role as a driver of ccRCC lipid accumulation and expression of CA9 and ENO1 cancer biomarkers." (PMID 34970493, 2021). "Targeting of ENO1 in combination with chemotherapy may be beneficial in patients with drug resistant cancers given its emerging role in chemoresistance." (PMID 33584813, 2020). "ENO1 showed a single 3′-UTR form suggesting that this is the predominant form in cancer cells." (PMID 32029502, 2020).
cancer (continued). "Therefore, ENO1 can be considered an oncoprotein critical for maintaining several “hallmarks of cancer”, particularly sustained proliferative signaling, deregulated energy metabolism, apoptosis resistance, and activation of invasion and metastasis." (PMID 33584813, 2020). "Furthermore, ENO1 was shown to influence proliferation, metastasis, and drug resistance in cancer cells by participating in the Warburg effect." (PMID 33067426, 2020). "Further to our previous statement that ENO1 could promote cancer progression via stimulating cell proliferation, increasing invasion and migration, and other mechanisms, ENO1 may lead to a late stage on the aspect of metastasis." (PMID 33643901, 2020). "In addition to its glycolytic function, ENO1 plays a crucial role in cancer cell invasion and metastasis, in part because it also acts as a plasminogen receptor." (PMID 32197468, 2020). "ENO1 autoantibodies have been included in TAA panels for cancer immunodiagnosis." (PMID 33584813, 2020). "However, the potential mechanisms involved in the regulation of ENO1 in cancers needs to be further explored." (PMID 33643901, 2020). "While these autoantibodies may occur in cancer patients independent of CAR, a recent study showed that vision loss and anti-retinal autoantibodies occur in at least 20 different human cancers, with ENO1 being the most frequent target of these antibodies." (PMID 33584813, 2020). "The evidence indicates that the ENO1 signaling axis might serve as a potential target for the treatment of cancer." (PMID 32013122, 2020). "Knockdown of ENO1 blocked CD47-mediated cancer cell proliferation and metastasis." (PMID 32226539, 2020). "In addition, we observed that exposure of cancer cells to LPS triggers protein arginine methyltransferase 5 (PRMT5)-mediated monomethylation of arginine 50 in ENO-1 and thus enhances cell surface expression of this protein." (PMID 31106201, 2019). "For instance, LPS potentiated ENO-1 exteriorization in monocytes and in cancer cells." (PMID 31106201, 2019). "Furthermore, ENO-1 depleted cancer cells evaded the “glycolytic shutoff” by enhancing mitochondrial electron flux followed by increased oxygen consumption, thus restoring oxidative phosphorylation." (PMID 31106201, 2019). "Dys-regulation of ENO1 is widely observed in cancer disease." (PMID 31431517, 2019). "ALDOA and ENO1 were both found to be involved in tumorigenesis in different cancer types." (PMID 31847435, 2019). "Thus, this study highlighs the key role of ENO-1 in the regulation of the Warburg effect in cancer cells." (PMID 31106201, 2019). "Finally, growth factors, like TGF-β1 and EGF enhanced extracellular transport of ENO-1 in cancer cells." (PMID 31106201, 2019). "Despite a large number of studies demonstrating the active role of cell surface bound ENO-1 in invasion of immune, cancer cells and bacteria, the molecular mechanism driving ENO-1 translocation to the cell surface remains unclear." (PMID 31106201, 2019). "Several studies have reported ENO1-mediated metabolic reprogramming in cancer cells." (PMID 30242159, 2018). "ENO1 is over-expressed in many cancers, including pancreatic cancer." (PMID 29462900, 2018). "In addition, the presence of autoantibodies to ENO1 in other cancer patients renders ENO1 a good molecular candidate target in other types of cancers too." (PMID 29462900, 2018). "Because PKM2 is an essential enzyme for regulation of aerobic glycolysis in cancer cells, we further determine that NEK2 expression is increased in high-risk patients and positively correlates with aerobic glycolysis genes including HK2, ENO1, and LDHA." (PMID 28086949, 2017). "Data analyses based on multiple bioinformatics tools produced a large body of biologically meaningful information, and revealed a number of genes such as SAMHD1, G6PD, GPD2 and ENO1, which have been reported to be related to immune response, blood biology, bone remodeling, and cancer respectively." (PMID 27878450, 2017).
cancer (continued). "The increased expression of ENO1 in some cancers was resulted from high mRNA levels." (PMID 28548950, 2017). "These included Eno1, LDHB, NPM1, PKM2 and KPNA2, which are commonly overexpressed in NSCLC, are associated with poor prognosis, and are therefore potentially relevant targets for cancer immunotherapy." (PMID 29258618, 2017). "Furthermore, exogenous Eno-1 expression promoted cancer cell proliferation, migration, invasion, and tumorigenesis." (PMID 26918350, 2016). "Hence, ENO1 has been considered as a potential candidate for targeted therapeutic intervention of cancer." (PMID 26882120, 2016). "However, compared with cancer angiogenesis, there is very limited understanding of glycolytic enzymes such as ENO1 in CNV." (PMID 26882120, 2016). "In this study, we have investigated the requirement of ENO1 for maintaining the Warburg effect in cancer cells and we have evaluated whether ENO1 silencing was effective in impairing the growth of cancer cells." (PMID 26734996, 2016). "The effect of ENO1 silencing opens new possibilities for cancer treatment, based on a combination between ENO1 targeting and therapies that are able to increase oxidative and metabolic stress, such as chemotherapy and radiation, or glutaminase and oxidative phosphorylation inhibitors, respectively." (PMID 26734996, 2016). "Indeed, overexpression of PLG-R including actin (ACT), enolase-1 (ENO-1), cytokeratin 8 (CK8) and annexin 2 (ANX2) has been associated with poor prognosis and resistance to chemotherapy of cancer patients." (PMID 25407528, 2014). "ENO1, a multifunctional protein, is a glycolytic enzyme which is highly expressed in liver tissue and cytoplasm of hyperplastic bile ducts and overexpressed in different cancer types." (PMID 25058392, 2014). "ENO-1 was found to be overexpressed in more than 20 types of human cancer." (PMID 25407528, 2014). "Here, (i) ENO-1 on monocytes, neurons, carcinoma cells, lymphoid cells, myoblasts and pathogenic bacteria; (ii) CK8 on carcinoma cells; (iii) p11 on endothelial cells; and (iv) glyceraldehyde-3-phosphate dehydrogenase (GAPDH) on bacteria are the best characterized ones." (PMID 25407528, 2014). "The expression of ENO1 on the cell surface was also observed in other cancers." (PMID 23894455, 2013). "ENO1 is the frequently deregulated in various types of cancer." (PMID 23504277, 2013). "Furthermore, aberrant expression of ENO1 has been verified in several cancer types." (PMID 40264038, 2025). "Taken together, we focused on these two cancer cell lines and proposed an antibody-based drug combination therapy, that is, the anti-ENO1 antibody combined with MET could reverse drug resistance caused by CSCs in conventional treatments (DDP or CTX), and preliminarily explored the mechanism." (PMID 38515460, 2024). "In parallel, we believe that antibodies combined with small-molecule drugs might provide a promising direction for drug repositioning and other cancer treatment against drug resistance, and anti-ENO1 antibody combined with MET might serve as a potential precursor platform for screening ADC." (PMID 38515460, 2024). "Therefore, we expect that IL-32 regulation by ENO1 could be applied to treat cancers with inflammatory responses as well as inflammatory diseases." (PMID 38675491, 2024). "Moreover, some studies have found that anti-ENO1 antibody could reduce the proliferation and invasion of cancer cells." (PMID 38515460, 2024). "Additionally, TYRO3 could inhibit the EMT process by down-regulating ENO1, which may be achieved by interfering with energy metabolism in cancer cells." (PMID 37116196, 2023). "We performed differential expression testing to found that cluster C3 over-expresses ENO1, BNIP3, PGK1 and LDHA, 4 genes associated with hypoxia (absolute log fold change above 0.5 and Wilcoxon test p-values below 0.01), that have been previously associated with cancer progression." (PMID 37917660, 2023). "Furthermore, Eno1 is modulated by HIF-1α in many cancer cells." (PMID 37125075, 2023).
cancer (continued). "In addition, overexpression of ENO1 have been found in many cancer types." (PMID 34671213, 2021). "Alpha-enolase (ENO1) is one of the enzymes of glycolysis that is shown to be overexpressed and contribute to the Warburg effect and its inhibition using phophonoacetohydroxamate (PhAH) or SF-2312 has been proven to be effective for many cancer cell lines in vitro." (PMID 33915900, 2021). "Moreover, it is well documented that ENO1 might act as an autoantigen in several cancer 40, 41, reflecting the greater immunologic reactivity and enhanced immune surveillance for cancer cells." (PMID 33628097, 2021). "The ENO1 may be a potential marker for the cancer immunotherapy." (PMID 34671213, 2021). "However, data concerning the impact of ENO1 in cancer conflict." (PMID 33628097, 2021). "To the best of our knowledge, this study is the first to elucidate the mechanisms that underlie the anti-cancer properties of MSPA, which we reveal were mediated through the simultaneous suppression of key enzymes in glycolysis and the tricarboxylic acid cycle, namely ALDOA, ENO1, and FH." (PMID 34681284, 2021). "Similarly, two other genes, GAPDH and ENO1, promote cancer progression in GBM." (PMID 34831287, 2021). "Additionally, increased ENO1 expression has been observed in different types of drug-resistant cancer cells, suggesting the potential use of ENO1 as a biomarker for drug resistance and as a target for cancer therapy." (PMID 33643901, 2020). "Besides the role of ENO-1 in metabolic shift of cancer cells, ENO-1 may also regulate metabolic processes in other cell types, including pulmonary artery smooth muscle cells (PASMCs)." (PMID 31106201, 2019). "We found that exosomes loaded with ENO-1 may enhance cancer cell migration and invasion." (PMID 31106201, 2019). "In addition, ENO-1 has been found to be overexpressed in more than 20 types of human cancer." (PMID 31106201, 2019). "However, overexpression of ENO1 reversed the effect of GRN A on migration of cancer cells significantly; the number of migrated cells was increased to 112 ± 16 in ENO1 transfected cancer cells treated with GRN A, compared with that in cells transfected with the control constructs." (PMID 28415822, 2017). "In general, the associations between Carbon Metabolism and Pathway in Cancer genes become weaken in HCC, whereas the associations between a number of genes are enhanced, especially those in the 22 up-regulated carbon metabolism genes group (such as HK1, PGK1, ENO1, PGLS, RPE)." (PMID 27363021, 2016). "Interestingly, ENO1 plays different roles in different types of cancer." (PMID 25951350, 2015). "Although increased angiogenesis is a hallmark of cancer, the early pre-leukemic changes are characterized by reduced number of EC, reduced VEGFR1, and -2 signaling, and increased expression of the HIF-1α target genes Pgk1- and Eno1 by CD31+ CD45- Ter119- cells." (PMID 26308666, 2015). "Despite these facts, an increasing body of evidence suggests that ENO-1, present on the outer leaflet of the plasma membrane of cancer cells, may also modulate pericellular proteolytic activity and thus contribute to cancer progression and metastasis." (PMID 25407528, 2014). "Mechanistically, treatment downregulated key nucleotide biosynthesis genes (DHFR, TK1) and the glycolytic enzyme gene (ENO1), while upregulating the oxidative stress response gene SLC7A11 (18.32-fold), suggesting disruption of cancer metabolic pathways." (PMID 42074264, 2026). "BMDMs or THP-1 cells from WT cancer cells suppressed the proportion of activated CD8+ T cells, as indicated by Ki67, IFN-γ, and GZMB expression, compared to those from ENO1-KO cancer cells." (PMID 40665335, 2025). "ENO1 is a moonlighting protein that performs multiple biochemical functions, and is a critical regulator of AKT phosphorylation in several types of cancers." (PMID 40533767, 2025).
cancer (continued). "Enolase 1 (ENO1), a key glycolytic enzyme, plays an important role in multiple pathological processes, including cancer development." (PMID 41231037, 2025). "Given the limited information, more studies are required to investigate the malignant functions of ENO1 and ENO2 in both cancers before a conclusion can be reached." (PMID 40214422, 2025). "The interaction between ENO1 and other proteins, such as protein arginine methyltransferase 5 (PRMT5), further exhibits its impact on cancer." (PMID 38611852, 2024). "Enolase 1 (ENO1), also known as alpha-enolase, is a multifunctional cancer protein which is widely expressed in multiple cell types." (PMID 39450258, 2024). "Enolase 1 (ENO1), plays a vital role as a glycolytic enzyme in cellular energy metabolism and is overexpressed in more than 70% of human cancers." (PMID 38840205, 2024). "In the targeted therapy of cancer, regulators such as hexokinase 2 (HK2), pyruvate kinase M2 (PKM2), enolase 1 (ENO1), and lactate dehydrogenase A (LDHA) are crucial for the glycolytic pathway." (PMID 39484162, 2024). "Paradoxically, CM was enriched with PABPC1, ENO1, and MSN, all of which have been considered oncogenic since their elevated transcript levels in cancer tissues significantly reduce the survival rate." (PMID 36923539, 2023). "As in several other cancer types, OCSCC cells collected from patients and the model oral squamous cell carcinoma (OSCC) cell line CAL-27 show increased ENO1 expression." (PMID 36768425, 2023). "ENO1 and PGRN have been reported to suppress ferroptosis in cancer cells or neurons, we found for the first time that these two genes associated with ferroptosis are up-regulated in RA." (PMID 37492576, 2023). "It was found that the expressions of ENO1, ENO2, and ENO3 of PANC-1 cells were increased under high-fat conditions, and the migration and invasion ability of cancer cells was enhanced." (PMID 37731842, 2023). "A chimeric anti-ENO1 mAb inhibits ENO1-mediated GSK3b inactivation, promotes ubiquitination and degradation of SLUG protein, and thus attenuates cancer cell invasion." (PMID 37795365, 2023). "Lastly, we examined the impact of the expression of ENO1, MSN, Mtdh, and PABPC1 on the survival rate of cancer patients." (PMID 36923539, 2023). "The results showed that ENO1, PFKFB3, NSDHL and SQLE were primarily detected in the in the cytoplasm of cancer cells in HNSCC tissues and the expression of these protein in recurrent HNSCC was significantly higher than that in normal tissues." (PMID 36841765, 2023). "Enolase (ENO-1), which converts 2-phosphoglycerate (2PG) to phosphoenol pyruvate (PEP), is emerging as a promising target for cancer therapy, partially owing to its diverse functions apart from being a major enzyme in glycolysis." (PMID 36768924, 2023). "Membrane-anchored ENO1 acts as a plasminogen receptor which converts plasminogen into plasmin and promotes ECM degradation, cancer cells invasion, migration and metastasis." (PMID 37449059, 2023). "ENO1, as an RNA-binding protein, can accelerate the messenger RNA decay of ACO1 in cancer cells, leading to repression of ferroptosis." (PMID 37492576, 2023). "Concerning the RFS, high expression of ENO1 was significantly related to poor prognosis of BRCA, LIHC, SARC, PAAD, and TGCT cancers." (PMID 36845730, 2023). "Our clinical stage ENO1 blocking antibody, HL217 (previously published as HuL227), has demonstrated its anti-cancer activity via reducing cell migration in vitro and in vivo in the pre-clinical studies of prostate cancer." (PMID 37964270, 2023). "Thus, ENO1 expression might be related to malignant tumor development." (PMID 35925486, 2022). "Under hypoxia, cancer cells tend to upregulate c-MYC, which simultaneously raises the ENO1 level to promote glycolysis, and lowers the MBP1 level, to speed up cell proliferation." (PMID 35434271, 2022).